TIE1 (tyrosine kinase with immunoglobulin like and EGF like domains 1)
Description:
Transmembrane tyrosine-protein kinase that may modulate TEK/TIE2 activity and contribute to the regulation of angiogenesis.
Synonyms: TIE; JTK14; LMPHM11
Tractability: Small molecule: a high-quality ligand is known; it belongs to a druggable protein family. Antibody: UniProt places it where antibodies can reach, with high confidence; its Gene Ontology location is reachable by antibodies, with high confidence; UniProt predicts a signal peptide or a membrane-spanning region. PROTAC: a small molecule that binds it is known.
Target class: TK protein kinase group; Enzyme; Tyrosine protein kinase Tie family; Protein Kinase; Kinase
Chemical probes: BAY-826 (high quality)
Gene: Protein-coding gene on chromosome 1 (43,300,971 to 43,323,108, forward strand). Ensembl gene ENSG00000066056.
Subcellular location: Cell membrane
Gene Ontology:
Molecular function: protein binding; transmembrane receptor protein tyrosine kinase activity; ATP binding; protein kinase activity; protein tyrosine kinase activity
Biological process: aortic valve morphogenesis; branching involved in lymph vessel morphogenesis; cell surface receptor protein tyrosine kinase signaling pathway; lymphatic endothelial cell differentiation; mesoderm development; positive regulation of angiogenesis; regulation of endothelial cell proliferation; regulation of extracellular matrix assembly; signal transduction; tissue remodeling; response to retinoic acid; tissue development; vasculogenesis
Cellular component: plasma membrane; receptor complex
Genetic constraint (gnomAD): Loss-of-function variants: 88 observed, 128.47 expected, observed/expected ratio (o/e) 0.69, 90% interval 0.58 to 0.82. The upper end of that interval is the gene's LOEUF score, 0.82, which puts it in group 3 of 6, group 1 being the genes least tolerant of losing a copy. Missense variants: 1,390 observed, 1,555.9 expected, observed/expected ratio (o/e) 0.89, 90% interval 0.85 to 0.93. Synonymous variants: 568 observed, 621.14 expected, observed/expected ratio (o/e) 0.91, 90% interval 0.85 to 0.98.
Homologues: Orthologues: chimpanzee TIE1 (99% identical), macaque TIE1 (98% identical), dog TIE1 (93% identical), mouse Tie1 (93% identical), guinea pig TIE1 (92% identical), rat Tie1 (92% identical), pig TIE1 (92% identical), rabbit TIE1 (59% identical), zebrafish tie1 (57% identical). Paralogues in human: TEK (46% identical), EPHA4 (19% identical), EPHA1 (19% identical), EPHA6 (19% identical), EPHA3 (19% identical), EPHB4 (19% identical), EPHB3 (18% identical), EPHA5 (18% identical), EPHA2 (18% identical), FGFR4 (18% identical), EPHA7 (18% identical), EPHB2 (18% identical), and 41 more.
Diseases named in the same sentence as TIE1 in open-access papers:
TIE1 is named in the same sentence as 94 diseases in open-access papers, as found by Europe PMC text mining. Sharing a sentence is not in itself a finding about the gene and the disease. The quoted sentences say what the papers report.
atherosclerosis (13 papers, 2015 to 2026). A disease characterized by the build-up of fatty material and calcium deposition in the arterial wall resulting in partial or complete occlusion of the arterial lumen. "Previous studies have demonstrated that TIE1, which expresses primarily in endothelial cells, is associated with vascular pathologies, including tumor angiogenesis and atherosclerosis." (PMID 36814284, 2023). "In particular, endothelial‐specific Tie1‐deficient mice display less atherosclerosis in comparison with wild‐type mice when crossed with ApoE knockout mice which are highly susceptible to atherosclerosis." (PMID 32406209, 2020). "The function of Tie1 in atherosclerosis was investigated in apoE-deficient mice using the conditional Tie1 allele." (PMID 27941161, 2017). "The EC specific receptor tyrosine kinase Tie-1, implicated in angiogenesis and vascular maturation, has been reported to be upregulated in inflammatory diseases such as rheumatoid arthritis and atherosclerosis." (PMID 31979004, 2020). "The same group detected a dose-driven decrease in atherosclerosis in Tie1-attenuated ApoE−/− mice, supporting the concept that Tie1 is a crucial controller of the endothelial reaction to perturbed shear stress." (PMID 39507419, 2024). "Tie1 deletion is known to decrease atherosclerosis in ApoE−/− mice by reducing vascular inflammation." (PMID 37476204, 2023). "We then use genetic deletion of Tie2 alone or in combination with Tie1 in arterial endothelial cells (AECs) in mice to explore Tie2 function in atherosclerosis." (PMID 37476204, 2023). "This indicated that arterial Tie2 function dominates over Tie1 function in atherosclerosis development." (PMID 37476204, 2023). "To understand how arterial Tie1 and Tie2 together affect atherosclerosis development, we next generated BmxCreERT2;Tie1fl/fl;Tie2fl/fl mice (Tie1;Tie2iΔAEC)." (PMID 37476204, 2023). "TIE1 is a tyrosine kinase receptor expressed by endothelial and hematopoietic cells and is functionally involved in major vascular diseases like atherosclerosis and tumor angiogenesis." (PMID 37775746, 2023). "We show that deletion of Tie2, or both Tie2 and Tie1, in the arterial endothelium promotes atherosclerosis by increasing Foxo1 nuclear localization, endothelial adhesion molecule expression and accumulation of immune cells." (PMID 37476204, 2023). "Ang2 is up-regulated in numerous human diseases, and Tie1 also promotes pro-inflammatory and pro-angiogenic signals in atherosclerosis and in tumours, respectively." (PMID 27941161, 2017). "The same group demonstrated a dose-dependent reduction in atherosclerosis in Tie1-attenuated ApoE−/− mice, giving credence to the idea that Tie1 is a critical regulator of the endothelial response to disturbed shear stress." (PMID 27027326, 2016). "Accordingly, EC-specific conditional deletion of Tie1 limited vascular inflammation and the development of atherosclerosis in ApoE-/- mice." (PMID 26436659, 2015). "Moreover, preclinical findings demonstrate that genetic deletion of TIE1 in mice retards vascularization and growth of tumor isografts and prevents atherosclerosis, with minimal impact on normal vascular homeostasis of adult mice." (PMID 39507419, 2024). "Therefore, we analyzed the phenotypes of mice with a combined Tie2 plus Tie1 gene deletion in atherosclerosis-promoting conditions." (PMID 37476204, 2023). "In this model, Tie2 function dominates in atherosclerosis over Tie1 function." (PMID 37476204, 2023). "Therapeutic blocking of Tie1 could have wider uses in other diseases such as atherosclerosis, diabetic retinopathy, and liver fibrosis." (PMID 32406209, 2020). "Our recent studies on the role of the TIE1 and TIE2 receptor signaling in atherosclerosis led us to ask how deletion of the Tie receptor signaling system in mice under homeostatic conditions affects coronary vessels." (PMID 41563573, 2026).
atherosclerosis (continued). "Our findings indicate that unlike Tie1, the Tie2 receptor functions as the dominant endothelial angiopoietin receptor that protects from atherosclerosis." (PMID 37476204, 2023). "Furthermore, an orphan receptor TIE1 seems to modulate the activities of signaling receptor TIE2, and thereby create the conditions for vascular inflammation in atherosclerosis, whereas its role remains elusive." (PMID 33302426, 2020).
breast carcinoma (12 papers, 2012 to 2025). "Our findings propose a novel function for TIE1 in breast cancer, distinct from its established role in endothelial cells." (PMID 41235901, 2025). "To investigate the function of TIE1 in breast cancer, we established a TIE1‐overexpressing MM231 cell line (MM231‐TIE1)." (PMID 41235901, 2025). "In this study, we demonstrated that TIE1 expression correlates with poor prognosis in breast cancer patients and is highly elevated in the Claudin‐low subtype, which largely overlaps with TNBC." (PMID 41235901, 2025). "In cancer research, TIE1 has been found to be upregulated in various cancers, including breast cancer." (PMID 41235901, 2025). "To elucidate the clinical significance of TIE1 in breast cancer, we analyzed its genomic profile using the Molecular Taxonomy of Breast‐Cancer International Consortium (METABRIC) cohort." (PMID 41235901, 2025). "The loss of MXRA8 also led to a decrease in the expression of genes associated with breast cancer, including ADAMTS1, TIE1, and BMP2." (PMID 37762032, 2023). "A recent study reported that high baseline circulating Tie-1 levels in breast cancer predict a worse prognosis." (PMID 34975347, 2021). "Although, to our knowledge, this is the first study to evaluate the prognostic role of plasma Tie1 levels in breast cancer patients, the study has some limitations." (PMID 31340773, 2019). "Metastatic breast cancer patients had significantly higher baseline plasma Tie1 levels than the healthy controls (p < 0.001)." (PMID 31340773, 2019). "Previous studies have reported strong Tie1 expression in malignant tissues, including breast cancer." (PMID 31340773, 2019). "Targeting of both Tie1 and Ang2 would be an interesting trial approach in the future for the treatment of breast cancer." (PMID 31340773, 2019). "Previous studies have suggested tumorigenic functions for Tie1 other than in angiogenesis, because it is expressed in various epithelial cancers, such as breast cancer 13, 14 gastric cancer 15, and thyroid cancer." (PMID 28464467, 2017). "Expression of Tie-1 has been reported in breast, gastric, colon, and thyroid cancers, but constitutive activation has only been proven in a breast cancer cell line." (PMID 22630170, 2012). "First, we found that TIE1 promotes tumorigenicity in breast cancer." (PMID 41235901, 2025). "Among various cancer types, breast cancer was the fourth most common to exhibit TIE1 amplification." (PMID 41235901, 2025). "Our findings suggest that TIE1 may serve as a potential molecular target and biomarker for Claudin‐low type breast cancer, and further research could have significant implications for its treatment." (PMID 41235901, 2025). "A high TIE1 expression predicts poor outcomes in breast cancer patients." (PMID 37762032, 2023). "In a study on breast cancer, the median circulating plasma Tie-1 level of metastatic patients was statistically significantly higher than that of healthy controls, and our previous experiment showed that cervical cancer cell lines secrete soluble Tie-1 (similar to ECs)." (PMID 34975347, 2021). "Additionally, we analyzed Tie1 concentrations in plasma from 10 healthy women participating in a breast cancer primary prevention study." (PMID 31340773, 2019). "Notably, TIE1 expression promoted tumorigenicity in a breast cancer cell line." (PMID 41235901, 2025). "Furthermore, TIE1 was highly expressed in Claudin‐low breast cancers, the same subtype as MM231." (PMID 41235901, 2025). "Moreover, TIE-1 overexpression was observed in many types of cancer, including gastric-, colon-, and breast-cancer cells, but the significance of TIE-1 overexpression in cancer remains unknown." (PMID 32604863, 2020). "Some of the alterations identified are drivers of different tumors and for VM formation: S1PR1 (breast cancer), PDGFRB, TIE-1 (melanoma), LOXL2 (hepatocellular carcinoma) and interestingly TCF-4." (PMID 36797281, 2023).
breast carcinoma (continued). "In breast cancer, enhanced expression of sTie-1 is positively correlated with lymphatic metastasis and shorter survival in hepatocellular carcinoma (HCC) patients, higher Tie-1 expression predicts poorer prognosis." (PMID 34975347, 2021). "Therefore, the loss of MXRA8 may influence intracellular signaling pathways that in turn alter the expression of genes like ADAMTS1, TIE1, and BMP2 that regulate breast cancer metastasis." (PMID 37762032, 2023). "However, the functional role of TIE1 in breast cancer has not yet been extensively investigated." (PMID 41235901, 2025).
melanoma (9 papers, 2010 to 2024). A malignant, usually aggressive tumor composed of atypical, neoplastic melanocytes. "Supporting these data, we detected significantly more expression of genes, including Cd31 and Tie1, in the tumors of the mice co-grafted with macrophages incubated with the fibroblast-derived melanosomes than in those only grafted with melanoma cells." (PMID 38719996, 2024). "First, it observed that highly aggressive melanoma cells (C8161, C918, and MUM 2B) expressed high levels of VE-cadherin and TIE-1 in contrast to less aggressive melanoma cells (C81-61, OCM-1A, and MUM-2C respectively)." (PMID 37298296, 2023). "The association between hematogenous metastatic spread of melanomas and high expression of ANGPT2 and TIE1 reported here is consistent with these observations." (PMID 29017512, 2017). "Using C57BL/6 or nude mice bearing subcutaneous tumors, we next performed immunohistochemistry for Tie1 on a number of cell lines derived from human or mouse cancers (HT29, a human colorectal cancer; PC3, a human prostate cancer; LLC, a mouse lung cancer; and B16, a mouse melanoma)." (PMID 28464467, 2017).
angiosarcoma (8 papers, 2010 to 2024). A malignant tumor arising from the endothelial cells of the blood vessels. "In fact, typical immunohistochemical expression profiles for angiosarcomas include upregulation of certain vascular-specific thyroxin kinase receptors, including, TIE1-2 and VEGFR1, VEGFR2 and downregulation of VEGFR ligand expression." (PMID 31228777, 2019). "The top most upregulated genes in angiosarcomas included angiogenic regulators such as TIE1, VEGFR2, SNRK, TEK, and VEGFR1, revealing that aberrant angiogenic signaling is a key feature of this sarcoma." (PMID 25374893, 2013). "Strong expression of ANGPT2, TIE1, and TEK mRNAs has been reported in cutaneous angiosarcomas, and Tie2 antagonists inhibit in vitro angiosarcoma cell survival and delay in vivo angiosarcoma tumor growth." (PMID 25374893, 2013). "In addition to including various vascular endothelial markers (ECSCR, TIE1, CD34, CDH5, ESAM), the angiosarcoma gene signature also included ROS1, supporting a possible broader role of ROS1 in the pathogenesis of this disease." (PMID 23637631, 2013).
liver fibrosis (8 papers, 2019 to 2023). "Meng Xu found that direct binding of LECT2 to Tie1 can inhibit portal vein angiogenesis, induce hepatic sinusoidal capillarization, and promote liver fibrosis." (PMID 37153080, 2023). "More importantly, our previous studies confirmed for the first time that LECT2 can bind to Tie1 as a ligand to promote the progress of liver fibrosis by affecting angiogenesis, and verified the conclusion in vitro and experimental animal models." (PMID 34631799, 2021). "Leukocyte cell-derived chemotaxin 2 (LECT2), a functional ligand of Tie1 expressed by hepatocytes and endothelial cells, promotes the capillarization of LSECs in the liver fibrosis rodent model." (PMID 33935770, 2021). "On the other hand, adeno-associated virus vector serotype 9 carrying LECT2 short hairpin RNA (AAV9-LECT2-shRNA) can target mouse LECT2 to inhibit LECT2/Tie1 signaling, thereby inducing portal angiogenesis, suppressing hepatic sinusoidal capillarization, and alleviating liver fibrosis." (PMID 37153080, 2023). "In addition, the combination of leukocyte cell-derived chemokine 2 (LECT2) produced by HCs and Tie1 expressed by LSECs also participates in the progress of liver fibrosis." (PMID 35837401, 2022). "As a functional ligand of endothelial cell-specific receptor Tie1, LECT2 promotes liver fibrosis by inhibiting portal angiogenesis and promoting capillarization of liver sinusoids in various liver fibrosis models." (PMID 35837401, 2022).
lymphedema (8 papers, 2020 to 2024). Excess fluid collection in tissues, causing swelling. "In conclusion, we present compelling evidence that TIE1 mutations are involved in the etiopathogenesis of primary lymphedema." (PMID 38820174, 2024). "In humans, similar to PIEZO1, mutations in FLT4, ANGPT2, and TIE1 have been associated with lymphedema, underscoring the conservation of function across species." (PMID 38747287, 2024). "Tyrosine kinase with immunoglobulin-like and EGF-like domains 1 (TIE1)—a cell surface protein involved in angiogenesis and lymphangiogenesis—is reportedly related to lymphatic dysfunction, as TIE1 gene variants were identified in 235 lymphedema patients." (PMID 34579131, 2021). "In this report, we attempted to link data in the literature and NGS analysis of TIE1 variants in lymphedema patients to investigate the role of the TIE1 gene in the development of lymphatic system malformations and predisposition for lymphedema." (PMID 32947856, 2020). "The case is familial: the proband’s mother has lymphedema and was found to carry the same TIE1 variant as the proband." (PMID 32947856, 2020). "The TIE1 receptor-deficient mouse model exhibited abnormal development of lymphatic vessels, indicating that the TIE1 gene may be associated with lymphedema progression." (PMID 34579131, 2021). "The main purpose of this study was to identify different variants in the TIE1 gene that could be associated with lymphatic malformations or dysfunction and predisposition for lymphedema." (PMID 32947856, 2020). "Variants in TIE1 could contribute to the onset of lymphedema." (PMID 32947856, 2020). "On the basis of our findings, we propose TIE1 as a candidate gene for comprehensive genetic testing of lymphedema." (PMID 32947856, 2020). "All in all, since animal models of TIE1 clearly show its function in the morphogenesis, remodeling and maturation of lymphatic vessels, TIE1 has been suggested as a gene involved in the development of lymphedema." (PMID 32947856, 2020). "In our study, we identified three different heterozygous missense TIE1 variants in 235 lymphedema patients (3/235; 1.28%), who tested negative for known lymphedema genes." (PMID 32947856, 2020). "Based on our results, we propose TIE1 as a candidate gene for genetic testing of lymphedema." (PMID 32947856, 2020). "Notably, our discovery that Ang2 and Tie1 were required for cell-surface VEGFR3 expression in the cutaneous lymphatic capillaries is consistent with previous findings that loss-of-function mutations of Ang2, and possibly of Tie1, predispose individuals to lymphedema and hydrops fetalis." (PMID 35763346, 2022).